CRP (C-reactive protein)
Diseases named in the same sentence as CRP in open-access papers (continued):
Sharing a sentence is not in itself a finding about the gene and the disease.
cancer (continued). "Fatigue and pain often co-exist in advanced cancer, and have been shown to have a significant association with the patient’s inflammatory state, especially with the levels of IL-6, IL-18, MCP-1, transforming growth factor (TGF)-β1, and CRP among others." (PMID 37837446, 2023). "And some recent studies have found that CRP is also an important marker of chronic inflammation and may have an etiological role in cancer." (PMID 36624433, 2023). "Further studies of the role of CRP are warranted in patients with cancer and IMDC." (PMID 37476185, 2023). "In addition, this protein-protein interaction network includes CRP, FN1 and PLAU, implicated in different ways with cancer risk or progression." (PMID 36649303, 2023). "IL‐6 stimulates CRP secretion, regulates stromal desmoplasia, promotes tumour‐induced immunosuppression and angiogenesis, inhibits apoptosis, stimulates cancer cell proliferation and facilitates metastasis, including formation of a pro‐metastatic niche in the liver." (PMID 36440611, 2023). "In addition, CRP levels were the highest in stage II cancer, and these differences were statistically significantly higher when compared to the control group (p < 0.001)." (PMID 37509572, 2023). "Our results indicate that appetite, along with fatigue, and the biochemical markers albumin and CRP/albumin ratio, could be considered valuable prognostic markers that may be used when assessing remaining survival time in patients with cancer." (PMID 37880704, 2023). "For example, it was found that CRP may predict poor outcomes in cancer cases but it also may have tumoricidal activity, so why are there therapeutic strategies proposed to lower CRP levels [1144]?" (PMID 37873776, 2023). "Finally, few early studies comparing pCRP and mCRP in animal models of cancer revealed that the conformation of CRP is a critical factor in eliciting the anti-metastatic effect." (PMID 37873776, 2023). "Some cancer cells themselves have been shown to express CRP." (PMID 37083267, 2023). "Furthermore, albumin has been shown to be a prognostic factor and predictive marker of treatment response in many cancer types when combined with C-reactive protein (CRP), fibrinogen, globulin, and lymphocyte." (PMID 37371699, 2023). "Consistent with a previous meta-analysis of frailty biomarkers in primarily non-cancer diagnoses of older adults, CRP and fibrinogen emerged as correlates of phenotypic and deficit accumulation frailty at pre-treatment and with phenotypic frailty during treatment." (PMID 37213604, 2023). "In cancer patients with persistent elevation of blood CRP levels, the inflammation is proposed to be sustained due to the ongoing inflammatory stimulus from the evolving tumor that potentiates hepatic and potentially, tumor intrinsic CRP production, leading to the “wound that never heals”." (PMID 37006231, 2023). "Additionally, HMB supplementation was found to lower serum CRP levels in malnourished elderly cancer patients." (PMID 37755304, 2023). "Furthermore, there are reports describing associations between e.g., high values of neutrophils, CRP and LDH and poor outcome among cancer patients receiving ICIs." (PMID 38049762, 2023). "Therefore, obviously, various contrasted data provide inaccuracies toward the real role of CRP (i.e., the tumoricidal activity of CRP compared to CRP use as a predictor of poor prognosis in cancer patients)." (PMID 37873776, 2023). "In addition to local inflammatory reaction, cancer patients often exhibit systemic inflammatory response, such as changes in peripheral blood cell counts and C-reactive protein (CRP), decreased hemoglobin and serum albumin (Alb) levels." (PMID 36635689, 2023). "However, since the treatment, stage, and CRP cut-off varied in those studies, it is difficult to distinguish between the effects of cancer-related inflammation and circulating CRP." (PMID 36996866, 2023).
cancer (continued). "Within this context it should be mentioned that a series of older studies conducted in various experimental, primarily murine, cancer models, using CRP, either in its pentameric form or injecting mCRP directly, found similar correlation with necrosis as demonstrated in the present study." (PMID 37006231, 2023). "Cohort studies on cancer and other diseases have agreed with the hypothesis of McMillan and Proctor, the doctors who first validated mGPS and suggested that raising the CRP level by >3 mg/L would achieve better predictive value." (PMID 36674837, 2023). "In clinical practice, blood sampling is the easiest and least invasive method of evaluating inflammation, with peripheral serum indicators, such as WBC and CRP, which are considered biomarkers of systemic inflammation, being correlated with prognosis and therapeutic effects in cancer patients." (PMID 37076988, 2023). "Furthermore, systemic inflammatory response biomarkers such as the CRP-to-albumin ratio and the Prognostic Nutrition Index are also known to have prognostic value in cancer." (PMID 36674837, 2023). "CRP is usually elevated in some diseases with chronic inflammation such as many cancers." (PMID 37122395, 2023). "CRP levels are used to detect inflammatory reactions and to help assess the progression of these diseases; hence, the increased plasma concentrations are directly related to tumor burden and cancer prognosis." (PMID 37174944, 2023). "In spite of these previous studies indicating an association of more than one biomarker in cases of cancer in dogs, there are no works evaluating the association of CA 15-3, CRP and LDH simultaneously in cases of CMNs." (PMID 36938312, 2023). "Overall, our results revealed that IMMUNEPOTENT CRP triggers endoplasmic reticulum stress accompanied by the increase of intracellular Ca2+ levels leading to mitochondrial damage and ROS production provoking regulated cell death on cancer cell lines." (PMID 37223080, 2023). "Cancer stage modified the association between randomized group and hs-CRP (Pinteraction=0.022) and IL6 (Pinteraction<0.001) but not sTNFαR2 (Pinteraction=0.39)." (PMID 38148846, 2023). "However, in these observational studies, it is difficult to differentiate between the deterioration of cancer-related inflammation and the clinical impact of elevated CRP levels themselves, because most studies analyzed peri-treatment CRP levels." (PMID 36996866, 2023). "Although the majority of these factors have been proven correlated with prognosis among cancer patients, including CRP, WBC, neutrophil‐to‐lymphocyte ratio, albumin, alkaline phosphatase, hemoglobin, and ECOG, this is the first study that shows their combined effect when incorporated into one model." (PMID 35871390, 2023). "CRP has been predictive of degree of cachexia as well as survival in cancer patients." (PMID 38022578, 2023). "Moreover, the correlation between CRP levels and prognosis in cancer patients has been well-established." (PMID 37765593, 2023). "The potential consequences should also be studied at the societal and the patient level if plasma CRP is included as a routine biomarker in patients referred with nonspecific signs and symptoms of cancer to a Diagnostic Unit." (PMID 36440611, 2023). "In addition, CRP suppresses the immune response and accelerates cancer migration and tumor microenvironment formation." (PMID 36674837, 2023). "An increase in the number of white blood cells in the blood, an increase in the percentage of neutrophils, a decrease in the percentage of lymphocytes, an increase in the N/L ratio, and an increase in CRP levels are known as poor prognostic factors for advanced cancer." (PMID 38143707, 2023). "Furthermore, the content of inflammation-related cytokines (interleukin-6 and CRP) was also significantly reduced in postoperative cancer patients." (PMID 37566134, 2023).
cancer (continued). "Cancer stage modified the association between randomized group and hs-CRP (P=0.022) and IL6 (P<0.001) but not sTNFαR2 (P=0.39)." (PMID 38148846, 2023). "Serial C-reactive protein (CRP) levels were measured in all participants recruited to a randomised controlled trial of CBD versus placebo in patients with symptoms related to advanced cancer." (PMID 37837446, 2023). "CRP is an acute-phase reactant elevated in inflammatory states and cancer." (PMID 35267634, 2022). "The most important explanatory variables for pulmonary abnormalities by three unrelated classifiers (C5.0, RF, and glmNet) included preexisting malignancy, multimorbidity, markers of systemic inflammation (IL-6 and CRP), and anti-S1/S2 antibody levels at the 60-day follow-up." (PMID 35131031, 2022). "To explore potential non-linear associations between CRP concentration and cancer risk, we estimated the associations with restricted cubic spline analysis." (PMID 36117174, 2022). "One may speculate that an inflammatory response inhibits early stages of oncogenesis for example by complement factor activation, which is regulated by CRP, promotes cancer cell death." (PMID 35459240, 2022). "Additionally, early increased CRP and IL-6 after the administration of nivolumab or pembrolizumab is also an indicator of cancer response in patients with non-small cell lung cancer." (PMID 37674988, 2022). "Cancer treatment that involves operative procedures can initiate a cascade of cytokine releases including IL-6 and C-reactive protein (CRP) which may induce proinflammatory changes conducive to aging." (PMID 35796942, 2022). "The distribution curve of CRP and LHR in patients with cancer showed that the levels of CRP and LHR increased with tumor stage progression, suggesting that inflammation may promote the incidence, stage, and progression of tumors." (PMID 35752767, 2022). "C-reactive protein is a sensitive biomarker of inflammation in various cancers." (PMID 36718344, 2022). "Hence, this study aimed to develop and validate a new inflammatory IR indicator (composed of CRP and TyG) to predict the survival of patients with cancer." (PMID 35795140, 2022). "In our study, we also observed an inflection point of the association between CRP and cancer risk at 3mg/L in different non-linear association patterns." (PMID 36117174, 2022). "There were no linear associations between genetically predicted CRP concentration and risk of overall cancer, as well as site-specific cancer (FDR-adjusted P > 0.05)." (PMID 36117174, 2022). "The score includes clinical parameters (ECOG performance score, previous chemotherapy and radiotherapy, cancer type) and biological variables (white blood cell count, C-reactive protein, haemoglobin and serum levels of tissue inhibitor of metalloproteinases-1, TIMP-1)." (PMID 36465336, 2022). "GPS, which is estimated with CRP and the albumin level which demonstrates the presence of systemic and local inflammation, has also been identified as a prognostic indicator for both survival and cancer progression." (PMID 34845844, 2022). "In addition, a high pretreatment CRP level was a consistent prognostic indicator of poor OS and cancer-specific survival (CSS) in patients with orohypopharyngeal squamous cell carcinoma." (PMID 35847918, 2022). "We conducted a pan-cancer analysis to comprehensively assess the role of CRP, including linearity and non-linearity associations." (PMID 36117174, 2022). "Therefore, general inflammation markers like C-reactive protein (CRP), leucocytes and lymphocytes have been suggested as prognostic biomarkers in cancer." (PMID 35027001, 2022). "Additionally, the Western dietary pattern has been correlated with pro-inflammatory markers associated with cancer-related fatigue, including tumor necrosis factor (TNF)-α, C-reactive protein, interleukin (IL)-6, and IL-8." (PMID 35454890, 2022).
cancer (continued). "Evaluation of CRP in cancer appears as a tool which may indicate disease severity and progression which can be useful for the therapeutic management of patients." (PMID 36361758, 2022). "Elevated CRP level is a poor prognostic marker in many cancers, including mRCC." (PMID 36551927, 2022). "Only three of the cancer patients had elevated C-reactive protein concentration before the surgery." (PMID 35410365, 2022). "Second, we selected CRP as an inflammatory marker in patients with cancer." (PMID 35752767, 2022). "There was a non-linear association between CRP and overall cancer risk with inflection point at 3mg/L (false-discovery rate adjust (FDR-adjusted) Poverall < 0.001 and FDR-adjusted Pnon-linear < 0.001)." (PMID 36117174, 2022). "A meta-analysis of almost 200,000 persons (11,000 cases) found an association between CRP and the incidence of all cancers (and with lung, but not breast, colorectal or prostate cancer taken individually)." (PMID 35406394, 2022). "Previous MR analysis has showed that the genetically elevated CRP concentration was probably to be a causal factor for gallbladder cancer, while not for cancers of colorectal, breast, or prostate." (PMID 36117174, 2022). "Cancer cells can produce IL-6 (which stimulates the production of CRP) or, in some cases, CRP." (PMID 35385679, 2022). "We examined the associations between five markers of unhealthy ageing; Growth Differentiation Factor-15 (GDF-15), N-terminal pro-brain natriuretic peptide (NT-proBNP), glycated hemoglobin A1c (HbA1C), C-Reactive Protein (CRP) and cystatin-C; with risks of cancer and cardiovascular disease (CVD)." (PMID 34935094, 2022). "While a 2014 study showed that a panel consisting of ALB, CA19-9, CRP, and IL-8 had the highest diagnostic value for distinguishing PDAC from controls, with this panel proving to be effective in identifying other cancers, such as breast, cervical, colorectal, prostate, and lung." (PMID 36969742, 2022). "CRP, dNLR, YKL-40, and IL-6 are biomarkers of systemic inflammation and elevated plasma levels are frequently seen in several age-related conditions, like cancer, and associated with the presence of vulnerability and frailty in older adults." (PMID 36233472, 2022). "Since albumin instability may reduce its prognostic predictive ability in cancer patients, we chose CRP-based mGNRI to construct the prognostic score in this study." (PMID 35433784, 2022). "Cancer cells could, in turn, produce several chemokines and cytokines, thus increasing the serum CRP level." (PMID 35847918, 2022). "The Glasgow Prognostic Score, an inflammation-based cancer-prognostic marker composed of serum elevation of CRP and decrease in albumin concentration, predicts patients with systemic inflammation as part of cancer cachexia and has been shown to have independent prognostic value." (PMID 36158184, 2022). "However, circulating levels of CRP can also be moderately elevated during chronic inflammation and cancer." (PMID 35752767, 2022). "Studies have shown that elevated levels of CRP before surgery can lead to poor cancer prognosis." (PMID 36290873, 2022). "Although observational analysis showed significant associations between CRP concentration and incident cancer risk in the prospective cohort, MR analysis did not support the causal relationship." (PMID 36117174, 2022). "In addition, fibrinogen has been shown to have the same predictive power as CRP in assessing adverse outcomes in cancer patients." (PMID 35606690, 2022). "CRP is one of the major indicators of acute phase inflammatory response including cancer." (PMID 36361758, 2022). "In this study, based on a large-scale prospective cohort study-the UK Biobank, we performed a pan-cancer analysis to assess the linear and non-linear associations between CRP and cancer risk." (PMID 36117174, 2022). "The increased level of interleukin 1 β (IL-1β) and IL-6, frequently observed in cancer, may amplify CRP production." (PMID 36361758, 2022).
cancer (continued). "In addition, circulating levels of CRP have been reported to be “markedly deranged” in patients with incurable cancer approaching death." (PMID 35223501, 2022). "CRP combined with LHR can improve the predictive power of patients with cancer." (PMID 35752767, 2022). "A non-linear association was also observed between CRP concentration and overall cancer risk with inflection point at 3mg/L (FDR-adjusted Poverall < 0.001, and FDR-adjusted Pnon-linear < 0.001)." (PMID 36117174, 2022). "To address whether this is the case also in cancer patients, we measured the inflammatory marker C-reactive protein (CRP) in plasma." (PMID 35309730, 2022). "In patients with GPS 1, those with low serum albumin and CRP levels may be undernutrition related with cancer, while those with high serum albumin and CRP levels may be pre-cachexic." (PMID 34519976, 2022). "Finally, CRP can lead to increased production of IL-6 and IL-8, which play a critical role in cancer cell metastasis." (PMID 35385679, 2022). "The blood test did not include CRP or erythrocyte sedimentation rate, which are indicators of inflammation, because it was associated with cancer screening of asymptomatic participants." (PMID 35197004, 2022). "CRP was significantly higher in cancer patients compared to the healthy control group." (PMID 35309730, 2022). "Additionally, C-reactive protein (CRP) concentration were considerably increased in childhood cancer survivors compared to the control group (0.56 ± 0.23 vs. 0.38 ± 0.13 mg/dL; p < 0.05)." (PMID 36142534, 2022). "Clinically, serum CRP, white blood cell, neutrophil and lymphocyte counts are the most commonly measured parameters to evaluate the degree of systemic inflammation response in cancer patients." (PMID 35812183, 2022). "When CRP was analysed as a continuous variable, the adjusted hazard ratios were 1.01(95%CI 1.00–1.03, p = 0.144, 1.02(95%CI 1.00–1.04, p = 0.057) and 1.00(95%CI 0.99–1.03, p = 0.860) for overall, cancer-specific and recurrence free survival respectively." (PMID 34802721, 2022). "The decrease in hemoglobin and albumin levels and the increase in C-reactive protein (CRP) levels observed in the BTC group may indicate carcinoma status." (PMID 36358797, 2022). "Moreover, cancer cells produce cytokines via autocrine pathways, such as IL-6 and IL-8, which in turn induce CRP production." (PMID 33685417, 2021). "Specific attention is given to in vitro and in vivo studies of CRP as an anti-cancer agent." (PMID 34552600, 2021). "Yet, little is known whether these two responses are related or opposing processes and why elevated CRP in relation to cancer is detrimental for clinical outcome." (PMID 34531864, 2021). "Accordingly, markers of systemic inflammation, including C-reactive protein (CRP), albumin, neutrophils, lymphocytes, neutrophil-to-lymphocyte ratio, platelet-to-lymphocyte ratio, and cytokines have been shown to be altered in patients with various cancers." (PMID 33680966, 2021). "In these studies, it has been suggested that tumor-associated inflammation is characterized by the infiltration of immune cells such as microglia/macrophages and the production of cytokines and chemokines, and CRP reflects the systemic response to this inflammation in cancer progression." (PMID 33584142, 2021). "As cancers can also induce chronic inflammation, on‐treatment CRP kinetics may have predictive value for immunotherapy treatment success." (PMID 34925829, 2021). "The C-reactive protein (CRP)/albumin (ALB) ratio serves as a prognostic marker for several cancers." (PMID 34154655, 2021). "The low-PNI group showed significantly older age, lower BMI, lower lymphocyte count, lower albumin concentration, longer prothrombin time, lower total cholesterol concentration, higher C-reactive protein concentration, and higher concentration of cancer antigen 19–9." (PMID 34130648, 2021).